CD44 (CD44 molecule (IN blood group))
Diseases named in the same sentence as CD44 in open-access papers (continued):
Sharing a sentence is not in itself a finding about the gene and the disease.
Stroke (20 papers, 2005 to 2025). Sudden impairment of blood flow to a part of the brain due to occlusion or rupture of an artery to the brain. "Surprisingly, we also detected a pronounced upregulation of Cd44 in stroke associated, proliferating OPCs." (PMID 39043661, 2024). "In contrast, at 4 and 8 weeks after stroke, the expression of Cd44, Spp1, and Cd74 (encoding CD44, Spp1, and CD74, respectively) was increased." (PMID 31888302, 2019). "Osteopontin (OPN), encoded by Spp1, is a cytokine‐like glycoprotein that binds to integrins and CD44 and is upregulated in stroke, CNS injury, and neurodegeneration." (PMID 40799188, 2025). "CD44+ microglia/macrophages appear in the infarct region following ischemia and CD44 expression persists into the chronic phase post-stroke." (PMID 41282250, 2025). "Although the molecular pathways regulating microglia/ECM interplay have not been fully elucidated, the interaction between the ECM protein serglycin (SRGN) and CD44 expressed by microglia has been recently described in an experimental model of stroke." (PMID 40943148, 2025). "In a rodent model of stroke, CD44 expression was found in both reactive astrocytes and proliferating oligodendrocyte precursor cells (OPCs) located at the lesional rim, close to OPN+ myeloid cells." (PMID 40943148, 2025). "Specifically, by analogy with astrocytes, findings suggest the involvement of CD44 in OPCs migration towards the lesion site, as pointed out in a model of demyelination and in a model of stroke." (PMID 40943148, 2025). "The regional cerebral blood flow (CBF) was unaltered during the stroke course after Cd44 gene knockout." (PMID 38287411, 2024). "Microglia and macrophage-derived Spp1 was predicted to signal back to both myeloid subsets, as well as stroke-specific OPCs (OPC_1) and stroke reactive astrocytes (AC_3 and AC_4) via Cd44." (PMID 39043661, 2024). "Stroke induced an increase in colonic epithelial Cd44 expression only in young female mice (P = .0003)." (PMID 37910478, 2023). "After stroke, CD44 seems to be upregulated in neural stem/progenitor cells (NSPCs) and microglia/macrophages at the penumbra area." (PMID 35639208, 2022). "At 8 weeks post-stroke, the top 10 genes were Cd44 (degree = 14), Fcgr2b (degree = 13), C1qb (degree = 13), Cd74 (degree = 12), C1qc (degree = 11), Cd14 (degree = 10), C4a (degree = 10), Spp1 (degree = 10), RT1-A2 (degree = 9), and Itgb2 (degree = 9)." (PMID 31888302, 2019). "Opn administration was recently reported to be neuroprotective in stroke whereas increased CD-44 mRNA seems to be harmful in ischaemia." (PMID 16318630, 2005). "Furthermore, CD44 is a hypoxia-responsive gene, and both endothelial and astrocytic cells upregulate CD44 under ischemic stress, amplifying HA/CD44 signaling during neuroinflammation, stroke, or trauma." (PMID 40943148, 2025). "Thus, our findings showed that microglial SRGN interacted with CD44 to promote microglial activation and post-stroke neuroinflammation." (PMID 38287411, 2024). "Thus, by targeting SRGN and its interaction with CD44, we can gain valuable insights into treatment of stroke." (PMID 38287411, 2024). "Moreover, Spp1 -> Cd44 signalling events from myeloid cells to stroke specific OPCs, reactive astrocytes and myeloid cells themselves ranged among the most robustly predicted interactions within our CCC analysis." (PMID 39043661, 2024). "In this respect, immunofluorescence staining of stroke tissues revealed the most prominent increase of osteopontin and CD44 receptor expression, and osteopontin-CD44 co-localization in the infarct core for endothelial cells and microglia during the late acute phase of ischemic stroke." (PMID 36463381, 2022). "Interestingly, TSG-6 elevation was coincident with increased HA levels in the lesioned brain and in the serum of stroke patients, together with an elevated expression of the HA receptor CD44 in damaged neurons and inflammatory mononuclear cells 3 to 17 days after stroke." (PMID 36982872, 2023).
Stroke (continued). "Alongside expression of RTN4A, comprising 76% total astrocytes in the injured cohort and 21% in control, we observed robust expression of GAP43, CD44 and KLF6, with both the percent of nuclei expressing these genes and the overall level of expression significantly increased after stroke." (PMID 34824275, 2021). "At 4 weeks post-stroke, the top 10 gene products in the PPI network were Cd44 (degree = 17), C1qb (degree = 15), Fcgr2b (degree = 14), Spp1 (degree = 12), Cd74 (degree = 12), C4a (degree = 12), C1qa (degree = 12), C3 (degree = 10), Cd14 (degree = 10), and Itgb2 (degree = 10)." (PMID 31888302, 2019). "However, CD8+/CD45+ cells in the ischemic brain were decreased in the IL‐2mAb treated stroke brain, while the MFI of CD44 on CD8+ T cells was significantly reduced (P < 0.01)." (PMID 30444079, 2019). "However, the interplay between SRGN and CD44 has not been explored in the context of stroke." (PMID 38287411, 2024).
adenoma (19 papers, 2011 to 2025). A neoplasm arising from the epithelium. "An important function of CD44 in the biology of the normal epithelial intestine and in adenoma formation is related to its capacity to associate with receptor tyrosine kinases, such as EGFR and MET." (PMID 29652830, 2018). "Our current data further demonstrate that the number of adenomas in AAs, which is significantly higher (48%) than White people, is also associated with 50–80% higher CD44+CD166− CSC phenotype in the colonic effluent and colonic mucosa from AAs than their White counterparts." (PMID 26990997, 2016). "CD44v6 and other ‘variable’ CD44 isoforms (CD44v4-10) earmark Lgr5+ intestinal stem cells (ISCs), that is, the cells of origin of intestinal tumors, and accordingly promote adenoma formation in vivo." (PMID 36346211, 2022). "According to a previous study, there was a significant difference between CRC cases and studied adenoma in terms of CD44 expression." (PMID 34837915, 2021). "Similar to Lef1 deletion, oncogenic KRAS has been shown to induce Myc and Cd44 expression and increase the dedifferentiation of the adenomas." (PMID 34788095, 2021). "All controls and 94% (32/34) of benign adenomas have been moderately stained (++) for CD44, while in malignant cases 21 out of 31 cases (68%) have been strongly (+++) stained for the same antibody." (PMID 33372636, 2020). "CD44s has been reported earlier to appear throughout the adenoma-carcinoma sequence 75, and CD44 tv that translate into standard CD44 proteins were also found to be more abundant in LS1034 xenografts than in cultured cells." (PMID 32685007, 2020). "In hypoxic, Tgf-β1-rich interiors of adenomas, we show that adenoma cells divide asymmetrically to produce cancer-generating cells highlighted by epithelial mesenchymal transition and a CD44/Zeb1 loop." (PMID 29930325, 2018). "Reduced adenoma formation was observed in mice CD44−/−/APCMin/+, which was completely rescued by the introduction of CD44v4 or CD44v6, but not by the standard CD44 isoform, CD44s." (PMID 29652830, 2018). "ADAM10 and ADAM17 regulate cell-ECM adhesion by shedding CD44, thereby stimulating CD44-mediated migration of adenoma cells through Rac activation." (PMID 28260841, 2017). "We found the number of adenomas and the proportion of CD44+CD166− CSC phenotype in the colon to be significantly higher in AAs than White people." (PMID 26990997, 2016). "This inference comes from analysis of miR profile of colonic mucosal cells enriched in CSCs which revealed a marked upregulation of miR‐1207‐5p not only in CSC‐enriched colonic mucosal cells but also in CD44+CD166− phenotype from AAs with adenomas." (PMID 26990997, 2016). "In conclusion, our current data show that AAs exhibit a significantly higher number of adenomas than their White counterparts, accompanied a marked increase in the proportion of CSCs in the colon, specifically CD44+CD166− phenotype." (PMID 26990997, 2016). "The increase in Cd44 protein in LApcL adenomas was confirmed by immunostaining." (PMID 34788095, 2021). "Normal epithelial cells in the colon express the standard form of CD44 (CD44s) whereas adenomas, carcinomas and CRC metastasis may also express CD44 variants (CD44v) containing additional exons that are coding for insertions in the membrane-proximal extracellular region." (PMID 26041882, 2015). "Meanwhile, the expressions of CD44, CD166, and CD133 are comparable between adenocarcinoma and adenoma organoids." (PMID 37667332, 2023). "Remnants of spontaneous adenomas from APCMin +/- mice treated with dasatinib and/or curcumin were analyzed for several cancer stem cell markers (ALDH, CD44, CD133 and CD166)." (PMID 21774804, 2011). "Still later, almost complete absence of CD44 was re-confirmed in 179 parathyroid cases, including normal glands, multiglandular parathyroid disease, adenomas and carcinomas." (PMID 35805976, 2022).
adenoma (continued). "Regarding CD44, intensity of staining was not significantly correlated between controls and benign adenomas." (PMID 33372636, 2020). "CGC arise at hypoxic sites in expanding adenomas and are marked by EMT and a CD44/Zeb1 loop." (PMID 29930325, 2018). "We found an evidence that a positive CD44/Zeb1 loop is initiated in small clusters of cells derived from asymmetrically dividing adenoma cells at sites of hypoxia, EMT, and Tgf-β1 accumulation in the interiors of expanding adenomas." (PMID 29930325, 2018). "In turn, CD44 was not induced, Zeb2 was not repressed, and cells displaying an E-cadherin−, Pten− pattern of EMT were diminished in adenomas." (PMID 29930325, 2018). "Racial differences in miRs were validated by TaqMan qRT‐PCR in CD44+CD166− CSC phenotype, isolated from AAs and White people with and without adenomas." (PMID 26990997, 2016).
pancreatic adenocarcinoma (19 papers, 2011 to 2025). "The adhesion and motility of pancreatic adenocarcinoma cells expressing different splice variants of the HA-binding cell surface receptor CD44 on these surfaces were investigated quantitatively." (PMID 22916191, 2012). "Liposomes coated with hyaluronic acid containing C12GEM demonstrated enhanced cytotoxic activity against pancreatic adenocarcinoma cell lines with CD44 overexpression." (PMID 40422749, 2025). "We found that HAVCR1 was associated with HHLA2, CD44 and TNFRSF4 in Liver hepatocellular carcinoma and Pancreatic adenocarcinoma." (PMID 35754803, 2022). "Using 178 pancreatic adenocarcinoma patient samples, CD44 and GABRP expressions were significantly co-expressed in the linear regression model." (PMID 35846884, 2022). "It was widely accepted that the surface markers CD133 and CD44 have been well defined for isolating CSCs from pancreatic adenocarcinomas." (PMID 24689055, 2014). "In this study, we utilized quantitatively functionalized supported membranes and studied the adhesion, morphological patterns, and motility of pancreatic adenocarcinoma cells expressing different CD44 isoforms." (PMID 22916191, 2012). "In this study, we sorted CD44+CD24+ESA+ CSCs in pancreatic adenocarcinoma cell line PANC-1." (PMID 24521357, 2014). "Furthermore, HAVCR1 expression was correlated with other immune molecules such as HHLA2 (Human endogenous retrovirus-H long terminal repeat-associating protein 2), CD44 and TNFRSF4 (TNF Receptor Superfamily Member 4) in Liver hepatocellular carcinoma and Pancreatic adenocarcinoma." (PMID 35754803, 2022). "Also, CD44 expression correlates with high Ki67, vimentin positivity, and N stage and may represent a potential target of novel therapeutic modalities in pancreatic adenocarcinoma patients." (PMID 28421110, 2017). "Flow cytometric analysis was used to determine the presence of CD44, CD24 and ESA on the cell surface of the pancreatic adenocarcinoma cell lines PANC-1." (PMID 24521357, 2014). "Recently, CSCs from pancreatic adenocarcinoma based on ALDH activity and the expression of the CD44 and CD24, and CD133 have been identified." (PMID 21304978, 2011). "Although ALDH expression was not examined in this study, co-expression of CD44 and CD24 was observed in ∼0.1% of CD133+ CSCs, again suggesting the possibility that multiple, distinct tumor-initiating populations exist in pancreatic adenocarcinoma." (PMID 21695188, 2011). "The expression patterns of the stem cell surface markers CD44, CD24 and ESA in pancreatic adenocarcinoma cell lines are diverse and not all CSCs sorted from pancreatic adenocarcinoma cell lines develop cell spheres, PANC-1 is a common pancreatic adenocarcinoma cell line used for study of CSCs." (PMID 24521357, 2014).
renal fibrosis (19 papers, 2014 to 2026). A final common manifestation of a wide variety of chronic kidney diseases characterized by glomerulosclerosis and tubulointerstitial fibrosis. "The CD44 expression score in the glomeruli and interstitium is associated with high levels of complement components in the urine and renal fibrosis." (PMID 37108355, 2023). "Our study suggested that an HA/CD44/TGFβ axis triggered by HAS2 overproduction due to COL4A5 deficiency could be strongly implicated in XLAS renal fibrosis." (PMID 40075271, 2025). "Our findings not only reveal a novel HA/CD44/TGFβ signaling axis that is implicated in Alport renal fibrosis but also suggest a promising strategy to inhibit renal fibrosis by specifically blocking HA/CD44 activation via the inhibition of HA production, CD44 activation or the HA‒CD44 interaction." (PMID 40075271, 2025). "During unilateral ureteral obstruction, CD44-deficient mice exhibited increased tubular damage, associated with decreased proliferation and increased apoptosis of tubular epithelial cells but decreased renal fibrosis." (PMID 28002484, 2016). "CD44 and miR-328 may serve as biomarkers and potential therapeutic targets for pressure-associated renal fibrosis." (PMID 24919189, 2014). "Interestingly, increasing evidence has revealed increased levels of CD44 in the kidney upon injury, nephritis and other pathological conditions, which are associated with the pathology of renal fibrosis." (PMID 40075271, 2025). "Its renal protective role was associated with reduced renal fibrosis, decreased activation of Akt and JNK, decreased expression of TGF‐β and IL‐6, and notably suppressed HA deposition and expression of HA receptors, CD44 and RHAMM." (PMID 41042601, 2026). "This study shows that CD44 expression marks renal tubular epithelial cells undergoing maladaptive repair and promotes the development of renal fibrosis." (PMID 40558504, 2025). "CD44+ cell activation and complement filtration contribute to renal fibrosis in glomerulopathies, with the strongest expression in focal segmental glomerulosclerosis." (PMID 40809316, 2025). "Studies have indicated that the enrichment of CD44 in the injured proximal tubules indicates renal epithelial cell injury, with its reduction contributing to a decrease in renal fibrosis." (PMID 38890983, 2024). "Previous studies have indicated that exosome-mediated activation of the SPP1/CD44 axis plays a crucial role in renal fibrosis." (PMID 39587675, 2024). "The urinary exosomes from patients with CKD greatly accelerated renal fibrosis, which was blocked by CD44 deletion." (PMID 35312232, 2022). "In animal models of renal fibrosis, CD44 knockout mice had lower collagen levels, myofibroblast transformation, and TGFβ signaling." (PMID 35280996, 2022). "This study demonstrates that exosome‐mediated activation of the OPN/CD44 axis plays a key role in renal fibrosis, which is controlled by β‐catenin." (PMID 35312232, 2022). "By analyzing the published GSE83610 dataset, CD44 was shown to be inversely related to IL-15 expression in the rat renal medulla of lithium-induced renal fibrosis." (PMID 35252184, 2022). "Gene deletion of β‐catenin in tubular cells (Ksp‐β‐catenin−/−) or gene ablation of CD44 (CD44−/−) greatly ameliorated renal fibrosis." (PMID 35312232, 2022). "We sought to determine the potential role of β‐catenin in regulating OPN/CD44 axis signalling in renal fibrosis." (PMID 35312232, 2022). "To test the role of CD44 in renal fibrosis, we counted renal interstitial fibrotic lesions after histological Masson staining." (PMID 35312232, 2022). "This study provides a novel mechanistic linkage of β‐catenin signalling and exosomal OPN/CD44 axis in the setting of renal fibrosis, and underscores an important therapeutic strategy for CKD." (PMID 35312232, 2022). "Exosome‐mediated activation of OPN/CD44 axis leads to the development and progression of renal fibrosis." (PMID 35312232, 2022).